EGFR (epidermal growth factor receptor)
Diseases named in the same sentence as EGFR in open-access papers (continued):
Sharing a sentence is not in itself a finding about the gene and the disease.
osteosarcoma (continued). "EGFR and PLAUR expression was also evaluated in 51 canine hemangiosarcomas and 31 canine osteosarcomas." (PMID 29218302, 2017). "The results confirm a higher expression level of CD146 on human osteosarcoma cells than HER2 and EGFR; antigens targeted by commercially available therapeutic antibodies." (PMID 27776176, 2016). "EGFR and cyclooxygenase-2 (COX-2) were found overexpressed in osteosarcoma in previous reports, so here we tried to explore the anti-osteosarcoma effect of ZD6474 alone or combination with celecoxib, a COX-2 inhibitor." (PMID 26050198, 2015). "In summary, our findings suggested that AREG promoted cancer cell motility of osteosarcoma and up-regulated the expression of ICAM-1 through the EGFR/PI3K/Akt/NF-κB signaling pathway." (PMID 26503469, 2015). "Overall these results imply that AREG and EGFR act through the PI3K/Akt-dependent signaling pathway to enhance ICAM-1 expression and cell migration in human osteosarcoma cells." (PMID 26503469, 2015). "In osteosarcoma, it was demonstrated that CMTM8, also known as CKLFSF8, suppresses the EGFR signaling pathway." (PMID 25551557, 2014). "EGFR and p-AKT signaling in osteosarcoma (OS) patients were analyzed for its relationship with cancer cell proliferation maker, Ki-67, using causal procedures and statistical tests." (PMID 19662227, 2007). "NCT03618381 (active, recruiting) includes epidermal growth factor receptor (EGFR)-specific CAR-T cells (Arm A) and EGFR and CD19-specific CAR-T cells (Arm B) in patients with osteosarcoma, Ewing sarcoma, rhabdomyosarcoma, synovial sarcoma, and clear cell sarcoma." (PMID 40227707, 2025). "PPI results showed that EGFR, CASP3, ESR1, HSP90AA1, and SRC may be potential targets for PA against osteosarcoma." (PMID 40991530, 2025). "To investigate the specific mechanisms, we used molecular docking techniques and found that EGFR might interact with DUSP3 and regulate osteosarcoma stemness." (PMID 39744427, 2025). "Therefore, anti-epidermal growth factor receptor targeting ligands were conjugated to the ICED-N, enabling the doxorubicin to target MG-63 osteosarcoma cells selectively." (PMID 38338373, 2024). "Furthermore, suppression of GPX4 and SOD2 reversed resistance to EGFR-TKIs in NSCLC and the induction of ferroptosis by impairing STAT3/Nrf2/GPx4 signaling enhances the sensitivity of osteosarcoma cells to cisplatin." (PMID 39681067, 2024). "Results demonstrated 1 of 21 patients with EGFR+ tumors achieved PFS at 4-months (vs 3 of 15 among EGFR- tumors), leaving authors to conclude that there was no significant activity among patients with EGFR+ osteosarcoma." (PMID 39417976, 2024). "Notably, three transcriptional modules out of the top ten MRs, CDK6, EGFR and PANX3, have already been proven to be critical mediators of pathogenesis in osteosarcoma." (PMID 37894336, 2023). "Curcuma has been used as an adjuvant treatment for osteosarcoma as a target of EGFR, but not available for breast sarcoma." (PMID 37635229, 2023). "Likewise, herein, we sought to determine the growth inhibitory profiles in a panel of osteosarcoma cells with moderate to high EGFR expression, including the U2-OS, MG-63, MNNG/HOS and KHOS/NP osteosarcoma cell lines (Figure A1)." (PMID 36980255, 2023). "In contrast, studies in highly invasive tumors such as osteosarcoma and malignant glioma have not reported activation of EGFR/MAPK by fibulin-3 but have shown instead direct activation of canonical TNF-alpha/NF-κB signaling." (PMID 36303838, 2022). "Several studies have shown a link between EGFR and BMP4 in osteosarcoma." (PMID 36685868, 2022). "Furthermore, another study found that EGFR expression in human osteosarcoma cell lines determined a greater expression of EGFR in MG-63, 143B, and MNNG-HOS cells and also an increase in EGFR mRNA level." (PMID 36234645, 2022). "By contrast, miR-342-5p had no significant inhibitory effect on EGFR in any of the three osteosarcoma cell lines." (PMID 35337159, 2022).
osteosarcoma (continued). "Immunofluorescence staining for phosphorylated EGFR (pEGFR) revealed that blue LED irradiation resulted in a dramatical decrease of pEGFR in a dose‐dependent manner in comparison with non‐irradiated group in both U‐2 OS and 143B osteosarcoma cells." (PMID 33960631, 2021). "Therefore, conjugation with EGFR aptamers not only increased the efficacy of Sali-loaded nanoparticles against osteosarcoma cancer cells, but also against CD133+ osteosarcoma CSCs." (PMID 34452081, 2021). "The identified immune-related predictive signature, including CD70, TNFRSF9, EGFR, PDGFD and S100A6, will facilitate the development of personalized therapy for osteosarcoma and provide new insights into the role of the tumor immune microenvironment in regulating patients’ responses to chemotherapy." (PMID 34016089, 2021). "Additionally, our experimental results confirmed that SCD3, EGFR, and MXI1 were remarkably up-regulated while CAVIN1 and TES were prominently down-regulated in osteosarcoma cells compared with normal cells." (PMID 35071320, 2021). "On the contrary, there has been no study on the application of an anti-EGFR mAb to EGFR-expressing canine osteosarcoma cell lines." (PMID 34944112, 2021). "Therefore, we investigated the effects of sodium cantharidate (SC), either as monotherapy and in combination with the EGFR inhibitor erlotinib, on STAT3 activation and osteosarcoma cell growth." (PMID 31422383, 2019). "Expression of both EGFR and PLAUR genes was detectable in all canine sarcomas, with hemangiosarcoma having higher levels of PLAUR mRNA, and hemangiosarcoma and osteosarcomas having approximately equivalent levels of EGFR mRNA, which paralleled results in human sarcomas." (PMID 29218302, 2017). "The relative radioresistance of osteosarcoma cells does not appear to be related to EGFR signalling exclusively." (PMID 27245053, 2016). "Although EGFR expression is common in osteosarcoma tumors, EGFRvIII (the most common mutant type of EGFR) is absent from osteosarcoma tumors." (PMID 27683579, 2016). "Although gefitinib and BIBW2992, two EGFR inhibitors, were reported not effective against osteosarcoma cells, we found in this study that ZD6474 exerts a direct anti-osteosarcoma effect in a dose-dependent manner." (PMID 26050198, 2015). "The inhibitory effects of ZD6474 on osteosarcoma cells in vitro are not related with the EGFR levels furtherly suggests that ZD6474 is a multiple-target tyrosine kinase inhibitor and plays anti-pliferation role also via inhibiting other signal pathways." (PMID 26050198, 2015). "This suggests that EGFR is not a central driver of osteosarcoma cell proliferation under in vitro cell culture conditions." (PMID 26526352, 2015). "Our data suggest that EGFR is not a major driver for osteosarcoma cell growth but contributes to starvation- and chemotherapy-induced stress survival." (PMID 26526352, 2015). "Finally, PDGFRα, Axl, PDGFRβ, RYK, EGFR, EphA2, EphA10 and IGF1-R are key targets of imatinib mesylate in osteosarcoma." (PMID 24599309, 2014). "In osteosarcoma, CMTM8 has been shown to suppress EGFR signaling." (PMID 25551557, 2014). "A study demonstrated efficient delivery of salinomycin to the EGFR−overexpressing osteosarcoma CSCs and cancer cells, which led to a reduced CSC population on osteosarcoma cells and CSCs by EGFR aptamer-bound, salinomycin-loaded polymer-lipid hybrid nanocarriers (EGFR-SNCs)." (PMID 40548119, 2025). "Additionally, co-administration of TGT with EGFR inhibitors, STAT3 inhibitors, and VEGFA inhibitors may enhance the anti-osteosarcoma effects of TGT, further inhibiting the development and metastasis of osteosarcoma." (PMID 38297292, 2024). "EGFR does not appear to be a major driver for osteosarcoma cell growth, but it may contribute to starvation and chemotherapy resistance." (PMID 35337159, 2022).
osteosarcoma (continued). "Moreover, in osteosarcoma cells, circ-ITCH could promote epidermal growth factor receptor (EGFR) protein levels by activating the EGFR/ERK pathway via miR-7 to promote cancer metastasis, migration, and invasion." (PMID 35327551, 2022). "In addition, the prognostic and clinicopathological significance of the EGFR expression of canine osteosarcoma and its relevance to EGFR-targeted drugs have not been fully elucidated." (PMID 34944112, 2021). "However, most current therapies targeting EGFR in osteosarcoma patients have not fulfilled expectations in clinical trials." (PMID 31422383, 2019). "However, effects of EGFR inhibition on radiation responsiveness in canine osteosarcoma have not been previously characterized." (PMID 27245053, 2016). "However, gefitinib and BIBW2992, two EGFR inhibitors, were reported not effective against osteosarcoma cells in a recent report, though osteosarcoma cells do over-express EGFR." (PMID 26050198, 2015). "Additionally, on the population of osteosarcoma stem cells, EGFR overexpression significantly lessened the inhibitory effect of DUSP3 upregulation, whereas the promoting effect of DUSP3 downregulation on osteosarcoma stem cell population was significantly inhibited upon EGFR downregulation." (PMID 39744427, 2025). "Moreover, the EGFR pathway is generally known to be one of the pathways which can increase PD-L1 expression in various cancers, although there have been no studies regarding this specifically in osteosarcoma." (PMID 38434518, 2024). "Since MYLK4 promotes the OS progress via the EGFR signal pathway, we attempt to combine the MYLK4 inhibitor with the EGFR inhibitor in order to see whether this combination synergistically inhibits the growth and metastasis of osteosarcoma in vitro and in vivo." (PMID 33980265, 2021). "Up until now, there have been no studies examining the relationship between IL6, EGFR, and STAT3 and PD-L1 using immunohistochemical expression in osteosarcoma patient subjects." (PMID 38434518, 2024). "Unlike EGFR or PDGFR, IGF1Rβ levels correlated with CYR61 and N-cadherin levels, and with the aggressiveness of osteosarcoma and overall survival." (PMID 30642298, 2019). "Unlike other osteosarcoma cell lines (HOS, MG-63, and KHOS/NP), U2OS cells lack expression of the EGFR, the well-known target of gefitinib; therefore, GAK is a putative bona fide target of gefitinib in these cells." (PMID 24971999, 2014).
thyroid cancer (117 papers, 2010 to 2026). "Epidermal growth factor receptor (EGFR), on the other hand, have been implicated in various cancer pathogenesis, including thyroid cancer." (PMID 36510281, 2022). "Samples were obtained from the archive between 2013 and 2019 and used to investigate BRAF, KRAS, and EGFR mutations in thyroid carcinoma samples." (PMID 36510281, 2022). "Overexpression of epidermal growth factor receptor (EGFR) is associated with thyroid carcinoma progression." (PMID 34819077, 2021). "The hub protein EGFR is linked to growth in many types of cancer, and cardiovascular diseases, and has been previously linked to thyroid cancers." (PMID 32093341, 2020). "TGFA and EGFR have been previously found to be co-expressed in thyroid cancer and have been associated with a more aggressive disease." (PMID 20877637, 2010). "However, research focusing on mutation profile, including the presence of KRAS and EGFR mutations in addition to BRAF mutations in thyroid cancer, is still rarely described, particularly in Indonesia." (PMID 36510281, 2022). "However, data on Kirsten rat sarcoma virus (KRAS) and EGFR mutations in thyroid cancer in Indonesia remain unavailable, except for BRAF-V600E, the most common BRAF gene mutation." (PMID 36510281, 2022). "BRAF, KRAS, and EGFR mutations in recurrent thyroid cancer may benefit from targeted therapies and further study on these mutations with their risk of recurrence, distant metastasis, and overall prognosis in thyroid cancers may be required." (PMID 36510281, 2022). "Our study highlights the frequent BRAF, KRAS, and EGFR mutations in thyroid carcinomas." (PMID 36510281, 2022). "Transforming growth factor-alpha (TGF-α), a key ligand of the epidermal growth factor receptor (EGFR), plays a pivotal role in promoting drug resistance across multiple cancer types, including thyroid cancer." (PMID 40843353, 2025). "For example, upregulation of the EGFR/ERK/AKT pathway has been observed in thyroid cancer cells with acquired LEN resistance, while co-administration of the EGFR inhibitor lapatinib has been shown to restore LEN sensitivity." (PMID 41155549, 2025). "In thyroid cancer K1 cells, EGFR co-immunoprecipitates with neural glia-related cell adhesion molecule (NrCAM), also a member of the L1CAM family." (PMID 39594667, 2024). "Vemurafenib (BRAFV600E inhibitor) resistance in thyroid cancer can be addressed by combining it with EGFR (Epidermal Growth Factor Receptor) inhibitors." (PMID 39281035, 2024). "In order to evaluate the binding efficacy of our peptides in other EGFR-overexpressing cancer cell types, we choose two different thyroid cancer cell lines (Cal62 and K1)." (PMID 37048151, 2023). "It has been demonstrated that the dual EGFR/HER-2 kinase inhibitor lapatinib sensitizes BRAF-mutant thyroid cancers to BRAF kinase inhibitors by blocking the rebound of MAPK/ERK pathway and the activation of the PI3K/AKT pathway." (PMID 36834830, 2023). "Overexpression of EGFR has been documented to a varying degree in thyroid cancer in previous studies." (PMID 38076095, 2023). "FDA-approved EGFR inhibitors, commonly employed as therapeutic agents for lung and thyroid cancers, can be successfully used to treat respiratory viruses." (PMID 38139259, 2023). "Lysophosphatidic acid receptor 3 (LPAR3) and epidermal growth factor receptor (EGFR) were direct targets of miR-133a-3p in thyroid cancer." (PMID 35314614, 2022). "We define rhabdoid (kidney and other soft tissues malignant tumor), gastric, neuroblastoma, breast, ovarian, and thyroid cancer cells (first cluster) as the most co-dependent on EGFR and methionine cycle genes." (PMID 36361596, 2022).
thyroid cancer (continued). "An elevated level of the methionine metabolism gene expression signature is present in EGFR-dependent cells, such as rhabdoid (kidney and other soft tissues malignant tumor), gastric, neuroblastoma, breast, ovarian, and thyroid cancer cells." (PMID 36361596, 2022). "For example, the overexpression of epidermal growth factor receptor (EGFR) is reported in the thyroid cancer database from The Cancer Genome Atlas (TCGA) and in aggressive ATC." (PMID 35159110, 2022). "A cluster of cancer cell lines, consisting rhabdoid (kidney and other soft tissues malignant tumor), gastric, neuroblastoma, breast, ovarian, and thyroid cancer cells, that are co-dependent on EGFR and methionine, was revealed." (PMID 36361596, 2022). "Although KRAS and EGFR mutations have been well investigated in NSCLC, however, study of these mutations on thyroid carcinoma is still limited." (PMID 36510281, 2022). "EGFR was also implied to be important for thyroid carcinoma proliferation and metastasis, and high EGFR level was reported in malignant thyroid cancer with wild type BRAF." (PMID 36510281, 2022). "LPAR3 was reported as a part of the ZEB1-AS1/miR-133a-3p/LPAR3/EGFR axis that promotes thyroid cancer progression by regulating PI3K/Akt/mTOR signaling." (PMID 32724813, 2020). "This consequently resulted in promoting the proliferative, migrative, and invasive abilities of thyroid cancer cells in vitro, and augmenting the tumorigenesis in vivo via activating epidermal growth factor receptor (EGFR)/PI3K/Akt pathway." (PMID 33158279, 2020). "The results suggest that EGCG is a tumor suppressor by increasing the apoptotic level in human thyroid carcinoma cells via EGFR/RAS/RAF/MEK/ERK signaling pathway." (PMID 30858760, 2019). "The significance of EGFR expression is also evaluated in human thyroid cancers using TCGA clinical cancer database of all 8215 tumors." (PMID 29849821, 2018). "These evidence indicates that EGFR has great potential to use as a biomarker and target for thyroid cancer therapy." (PMID 29849821, 2018). "In the present study, using a large-scale analysis platform, we demonstrated that EGFR is predominately expressed in thyroid cancer by introducing gene microarray database of all 1036 cancer cells and TCGA clinical tumor information from 8215 tumors." (PMID 29849821, 2018). "In tissue microarray sections, it is shown that EGFR is highly expressed in papillary, follicular, and the deadliest anaplastic subtype of thyroid cancers, compared to the low EGFR expression found in the normal thyroid gland." (PMID 29849821, 2018). "Both observations well-characterized thyroid cancers that indicate EGFR participates in the progression of an important proportion of cases." (PMID 29849821, 2018). "EGFR mediated downstream signal transduction and was overexpressed in an aplastic thyroid cancer cell lines, rendering this receptor a potential target for molecular therapy." (PMID 28938536, 2017). "Cell proliferation, cell cycle distribution, induction of apoptosis and EGFR and AKT signaling were evaluated in thyroid carcinoma cell lines bearing the BRAF V600E mutation in response to PLX4032." (PMID 29033690, 2017). "Of note, the combined treatment with gefitinib and vemurafenib or the exposure of EGFR-silenced thyroid carcinoma cells to vemurafenib induced synthetic lethality compared to single agents." (PMID 29033690, 2017). "Overexpression and autocrine activation of the epidermal growth factor receptor (EGFR) in thyroid carcinomas contributes to the activation of the RAS-MAP kinase cascade." (PMID 25879531, 2015). "A recent report evaluating several markers in human thyroid carcinoma found strong EGFR expression in invasive PTC and FTC." (PMID 22630170, 2012). "Our data indicate that activated EGFR also cooperates in thyroid cancer cell lines with the ADAM17/TACE sheddase in promoting ALCAM shedding and soluble ALCAM release." (PMID 21364949, 2011).